ME2 (malic enzyme 2)
Diseases named in the same sentence as ME2 in open-access papers (continued):
Sharing a sentence is not in itself a finding about the gene and the disease.
epilepsy syndrome (1 paper, 2023). A syndrome that has a characteristic cluster of clinical features and/or lectroencephalographic (EEG) findings that reflect underlying epileptic activity. "ME2 has been identified with a gene associated with epilepsy syndromes." (PMID 37217557, 2023).
Fibroadenoma (1 paper, 2020). A benign tumor of the breast characterized by the presence of stromal and epithelial elements. "Furthermore, the expression of seven step-changing proteins (KRT10, KRT1, KRT6E, PLIN1, HBA2, FHL1, and ME2) were decreased in fibroadenoma tissues compared to fibroadenoma adjacent and normal tissues." (PMID 33194682, 2020).
liver cancer (1 paper, 2023). An epithelial or non-epithelial malignant neoplasm that arises from the liver. "Here, we identified the role of ME2 in regulating liver cancer cells migration via increasing the pyruvate production, which binds to and increases β-catenin protein stability, thereby promoting cell migration and invasion." (PMID 37110198, 2023). "Here, we show the role of malic enzyme 2 (ME2) in promoting human liver cancer cell lines SK-Hep1 and Huh7 cells migration and invasion." (PMID 37110198, 2023).
manic disorders (1 paper, 2010). "ME2 gene expression is 5.6-fold lower in anterior cingulate tissue from post-mortem bipolar brains, associated with both psychotic and manic disorders including schizophrenia and bipolar disorders." (PMID 20824065, 2010).
mesothelioma (1 paper, 2019). A usually malignant and aggressive neoplasm of the mesothelium which is often associated with exposure to asbestos. "ME1 and ME2: The monoclonal antibodies ME1 and ME2, which were initially generated by immunizing mice with the mesothelioma cell line SPC111, have been used to study human cultured mesothelial cells and ovarian tumor cells." (PMID 30965570, 2019). "In combination with AUA1—an antibody which recognizes a human cell surface antigen on epithelial cells —ME1 and ME2 recognized both normal mesothelial cells and mesothelioma." (PMID 30965570, 2019).
oral squamous cell carcinoma (1 paper, 2020). "Our study investigated the expression of malic enzyme 2 (ME2) in human oral squamous cell carcinoma (OSCC) and associated pathological and clinical pattern." (PMID 32218701, 2020).
osteosarcoma (1 paper, 2022). A usually aggressive malignant bone-forming mesenchymal neoplasm, predominantly affecting adolescents and young adults. "In human osteosarcoma U2OS cells and normal diploid fibroblast IMR90 cells, the forced expression of ME1 or ME2, or the addition of a malic enzyme substrate, increased the cellular NADPH levels." (PMID 36612292, 2022).
schizophrenia (1 paper, 2008). A major psychotic disorder characterized by abnormalities in the perception or expression of reality. "A range of studies (proteomics, genomics, gene association studies) have linked schizophrenia with alterations in malate dehydrogenase cytoplasmic (MDHC, now known as malic enzyme 2)." (PMID 18545652, 2008).
Sepsis (1 paper, 2025). Sepsis is defined as life-threatening organ dysfunction caused by a dysregulated host response to infection. "For instance, gene module ME1 was downregulated, while ME2, ME3 and ME4 were upregulated in sepsis samples compared to healthy controls." (PMID 40965975, 2025).
cancer (26 papers, 2010 to 2025). A tumor composed of atypical neoplastic, often pleomorphic cells that invade other tissues. "ME2 is associated with the development of malignancies and is variably expressed in a number of cancers." (PMID 39528487, 2024). "ME2 overexpression has been associated with several cancer types including lung cancer, melanoma, or glioblastoma." (PMID 34932167, 2021). "A recent study reported that SIRT5 desuccinylates malic enzyme 2, thus facilitating mitochondrial respiration and cancer growth in CRC." (PMID 40164945, 2025). "Recently, some studies have reported that malic enzyme (ME) plays an important role in cancer development, while the involvement of ME2 in HCC remains still undetermined." (PMID 34427987, 2021). "Among multiple molecules and signals involving in cellular metabolism, ME2 was suggested to play crucial roles in modulating cell growth, proliferation, metabolism, and invasion of many types of cancer." (PMID 34427987, 2021). "For example, highly desmoplastic cancer types relying heavily on the interactions with the surrounding stroma, like gastric and pancreatic tumours, often have genomic deletions of ME2." (PMID 34932167, 2021). "Previous studies have indicated that ME2 promotes growth, transformation, and metastasis of malignant tumors." (PMID 34381734, 2021). "We found that most cancer cell lines express higher levels of ME1 than of ME2 and ME3, although some cell lines predominantly expressed ME2 and ME3." (PMID 28481367, 2017). "From a cancer standpoint, ME2 activity increases with progression to neoplasia in a rat tracheal epithelial line with similar findings in Morris hepatomas." (PMID 20824065, 2010). "The mitochondrial malic enzyme 2 (ME2), which is frequently elevated during carcinogenesis and may be a target for cancer therapy, catalyzes the conversion of malate to pyruvate." (PMID 39528487, 2024). "ME2 plays a critical role in mediating metabolic alterations in cancer cells." (PMID 37079187, 2023). "Furthermore, it was demonstrated that ME2 knockdown impairs the proliferation and the growth of different cancer cell lines." (PMID 31881713, 2019). "Previous studies have shown that ME2 may participate in cancer cell invasion and migration processes." (PMID 27166188, 2016). "Our findings suggest that ME2 is crucial for mitochondrial pyruvate and energy metabolism, as well as cellular respiration, and that ME2 inhibitors could be useful in the treatment of cancer or other diseases that involve these processes." (PMID 37217557, 2023). "In conclusion, EA or MDSA inhibit ME2-associated metabolism, particularly energy metabolism, suggesting that the inhibition of cell migration and invasion by EA or MDSA may be attributable to the suppression of energy production in cancer cells." (PMID 37217557, 2023). "However, only ME1 and ME2 were considered to play a role in cancer metabolism." (PMID 34932167, 2021). "However, the potential mechanisms by which ME2 regulates cancer cell migration remain unclear." (PMID 37110198, 2023). "ME2 is involved in the TCA cycle and regulates the glutamine metabolism in some cancer cells." (PMID 37110198, 2023). "In vitro ME2 activity inhibition was also investigated with the natural compound embonic acid which also shows a non-competitive inhibition against ME2 and a reduction of growth of H1299 cancer cells." (PMID 31881713, 2019).
cancer (continued). "ME2 is a mitochondrial NAD(P)+ isoform, and because it affects two cofactors, it plays a key role in physiologic and pathologic functions, including insulin release, rapidly proliferating cancer cells, as well as epithelial-mesenchymal transition (EMT)." (PMID 30332737, 2018). "ME2 has two cofactors, NAD+ or NADP+; therefore, this enzyme may be key for rapidly proliferating cancer cells to meet their metabolic demands." (PMID 27166188, 2016). "However, using a ME2 inhibitor alone may not be sufficient to cure AML, as cancer cells can adapt to altered metabolism." (PMID 37079187, 2023).
tumor (26 papers, 2007 to 2025). "Activated ME2 significantly enhanced mitochondrial respiration to counteract glutamine deficiency, promoting cell proliferation and tumor development." (PMID 39528487, 2024). "Thus, it would be of interest to further elucidate what physiological functions this newly discovered form of cytoplasmic ME2 has in addition to its tumor-promoting effects in PTEN-deficient or AKT-activated tumors." (PMID 38263319, 2024). "The mechanism by which depletion of ME2 causes tumor cell differentiation remains to be elucidated." (PMID 20824065, 2010). "Tumor size, tumor pathology grade, and ME2-R67K expression were also found to be positively correlated with each other." (PMID 39528487, 2024). "The clinical connection between the tumor and surrounding normal tissues of 73 HCC patients revealed that PRMT1 was strongly expressed in HCC and strongly linked with both ME2 methylation and poor clinical prognosis, which is consistent with our results." (PMID 39528487, 2024). "ME2 is an oncoprotein that promotes tumor cell proliferation and limits cellular senescence in the context of the genetic background of wild-type p536." (PMID 38263319, 2024). "Yet, silencing of ME2 apparently reduced the tumor growth derived form PTEN-depleted cells, further reinforcing the importance of ME2 in AKT1-mediated tumor growth." (PMID 38263319, 2024). "ME2 plays an important role in regulating the cell growth, proliferation, and invasion of a variety of tumor cells." (PMID 37110198, 2023). "In vivo, both the constitutive and conditional knockdown of ME2 in A549 cells slowed tumor growth and increased their killing in response to cis-platinum treatment or the direct injection of dimethyl malate." (PMID 33808495, 2021). "Previous studies have investigated that ME2 is significantly dysregulated and correlates with tumor progression." (PMID 34427987, 2021). "We demonstrated that human OSCC tissues expressed a high level of ME2, and the overexpression of ME2 is closely connected to a high pathological grade, lymphatic metastasis, large tumor size and human papillomavirus (HPV) (P < 0.001)." (PMID 32218701, 2020). "The most notable finding from this study was that overexpression of ME2 is correlated with high pathological grade, lymphatic metastasis, large tumor size and HPV." (PMID 32218701, 2020). "Of interest, ME2 is present in tumor mitochondria in levels proportional to the rate of cell division, while curiously it is essentially absent in liver, regenerating liver, and the mitochondria of other organs." (PMID 20824065, 2010). "We have provided the first evidence that the malic enzyme family member ME2 is important in tumor biology; in particular, in the differentiation program of K562 cells." (PMID 20824065, 2010). "We found that knockdown of ME2 led to diminished proliferation of tumor cells and increased apoptosis in vitro." (PMID 20824065, 2010). "In one group of 4 mice, each mouse received a vector control inoculation in one flank and an ME2 shRNA clone in the other, so that tumor comparisons would be controlled for each individual mouse." (PMID 20824065, 2010). "A striking phenotype that we observed upon ME2 knockdown, namely the induction of erythroid differentiation and the inhibition of tumor growth, has previously been observed by other manipulations that affect metabolic pathways in K562 cells." (PMID 20824065, 2010). "The possible functional involvement of ME2 in neoplasia is strongly suggested by its increased activity in tumor tissue." (PMID 20824065, 2010).
tumor (continued). "In conclusion our data indicate that ME2 plays a crucial role in modulating K562 cell differentiation and growth and highlight a novel role for ME2 as a potentially attractive target for tumor therapy." (PMID 20824065, 2010). "As a fumarate sensor in tumor cells, ME2 may dimerize in response to elevated fumarate concentrations, increasing its enzymatic activity and encouraging mitochondrial production and cell division." (PMID 39528487, 2024). "Moreover, the sh-ME2-WT group had the greatest levels of NADPH and GSH, but the sh-ME2-R67K group’s tumor tissues had far lower levels of NADPH and GSH than did the sh-ME2-WT group." (PMID 39528487, 2024). "Notably, ME2 activity is highly elevated in tumor cells and correlates with tumor progression, and NADPH generation and redox control capabilities confer potent oncogenic function to ME26,11." (PMID 38263319, 2024). "Finally, ME2, required for ATP production and tumor cell survival under glucose unavailability, is also overexpressed in multiple tumors and its deletion has been shown to decrease ATP production and induce cell death." (PMID 35148308, 2022). "ME2 knockdown significantly suppressed the tumor initiation and progression of MHCC97H cells." (PMID 34427987, 2021). "Our findings suggest that ME2 is critical for the tumor growth of HCC cells." (PMID 34427987, 2021). "They reported that depleting ME3 selectively killed ME2-null PDAC cells, and so hypothesised potential new specific targets for novel inhibitors in SMAD4-mutated tumours." (PMID 29329208, 2018). "Because ME2 mRNA expression was increased in the tumor samples, we first examined the ME2 protein level in three GBM cell lines, GBM8401, U87MG and LN229, and the ME2 levels in all three GBM cell lines were comparative to those of the positive control, HepG2 cells." (PMID 27166188, 2016). "Thus, through phosphorylation of ME2fl, AKT1 enhances the glycolytic capacity of tumor cells in vitro and in vivo, revealing an unexpected role for subcellular translocation switching of ME2 mediated by AKT1 in the metabolic adaptation of tumor cells to growth stimuli." (PMID 38263319, 2024). "In addition, ME2 knockdown also decreased triglyceride content in tumor tissues." (PMID 34427987, 2021). "Therefore, overexpression of ME2 was significant, which indicated abnormal mitochondrial respiration may come about higher pathological grade and larger tumor size." (PMID 32218701, 2020). "Here, we discovered a previously unrecognized mechanism by which tumor cells coordinate glycolysis and the mitochondrial TCA cycle via AKT1-mediated ME2 phosphorylation." (PMID 38263319, 2024). "Malic enzyme’s isoforms ME2 and ME3 reside in mitochondria whereas ME1 is cytosolic, and all of them are frequently overexpressed in tumor tissues of diverse origin." (PMID 26869992, 2016). "In this work, for the first time, we investigated the mechanism of ME2 methylation and observed that PRMT1 mediates the methylation of ME2 and prevents its ubiquitination, which increases its protein stability and enhances mitochondrial respiration and HCC tumor development." (PMID 39528487, 2024). "Moreover, PRMT1-mediated methylation of ME2 inhibits ME2-FBW7 interaction and ubiquitination-mediated degradation, promoting tumor cell survival and proliferation." (PMID 39528487, 2024). "It is possible that the knockdown of ME2 indirectly disrupts additional unidentified pathways that are of functional relevance in vivo e.g. critical for establishing tumor take but not manifest in vitro." (PMID 20824065, 2010).
infection (2 papers, 2019 to 2020). The state of being infected such as from the introduction of a foreign agent such as serum, vaccine, antigenic substance or organism. "In both fat depots, infection was associated with decreased expression of lipogenic genes, such as those encoding glucose transporter 4 (Glut4), malic enzyme 2 (Me2), and fatty acid synthase (Fasn)." (PMID 32409640, 2020). "In the same experiment, we also tested the recruitment of H3K9me1, me2, and me3 and observed that all three H3 marks are associated with the KSHV genome within 24 hr of de novo infection." (PMID 31682228, 2019).
nervous system diseases (1 paper, 2023). "Genes in ME2 were enriched in KEGG pathways related to some nervous system diseases and reactive oxygen species, which is a kind of chemical carcinogen; genes in ME14 and ME23 were enriched in the spliceosome pathway and the herpes simplex virus 1 (HSV-1) infection pathway, respectively." (PMID 36975828, 2023).
ME2 also shares sentences with these, for which no sentence is quoted: colorectal cancer (3 papers); glioblastoma (2); erythroleukemia (1); head and neck squamous cell carcinoma (1); Hepatic steatosis (1); idiopathic generalized epilepsy (1); Insulin resistance (1); malignant glioma (1); meningitis (1); myelodysplastic syndrome (1); non-small cell lung carcinoma (1); psychosis (1).